INS (insulin)
Diseases named in the same sentence as INS in open-access papers (continued):
Sharing a sentence is not in itself a finding about the gene and the disease.
Hypoglycemia (continued). "In both infants, hyperinsulinism was identified as the cause of hypoglycaemia, diagnosed by detectable insulin levels during episodes of hypoglycaemia (< 2.8mmol/L) coupled with hypoketonemia (β-hydroxybutyrate < 1.8 mmol/L)." (PMID 41084516, 2025). "Low risk of hypoglycemia, reduced need for insulin, and extremely rare probability of acute rejection have been reported with GLP-1RA." (PMID 40255815, 2025). "The combination of basal insulin and GLP‐1 RA provides effective glycaemic control and mitigates body weight gain and the risk of hypoglycaemia that are associated with insulin therapy." (PMID 40176458, 2025). "Exuberant levels of IGF-2 secreted by the tumor tend to cause hypoglycemia that mimics hypoglycemia caused by insulin-secreting PanNETs." (PMID 40522948, 2025). "These mutations impair the regulation of amino acid-induced insulin secretion, leading to leucine-sensitive hypoglycemia associated with moderate hyperammonemia." (PMID 40904956, 2025). "IDegLira was non‐inferior to basal‐bolus insulin in lowering HbA1c, with the added benefits of less weight gain and a lower risk of hypoglycaemia." (PMID 40678871, 2025). "Patients need to pay special attention to hypoglycemia risk assessment, especially for those on insulin treatment and following weight loss surgery." (PMID 40507585, 2025). "Knowledge of insulin self-administration, specifically at a low level, was associated with an increased risk of reported hypoglycemia." (PMID 40110390, 2025). "It is produced by anti-insulin antibodies that initially bind to insulin and subsequently bind off, causing hypoglycemia." (PMID 40584814, 2025). "The most critical limitation remains the risk of iatrogenic hypoglycemia, particularly with intensive glycemic control, as exogenous insulin administration cannot perfectly replicate physiological glucose‐responsive secretion." (PMID 40919135, 2025). "Sulfonylureas stimulate insulin secretion via pancreatic KATP channel modulation but increase the risk of hypoglycemia and weight gain." (PMID 41471118, 2025). "In general, individuals with advanced CKD have a high risk of hypoglycaemia due to decreased renal gluconeogenesis, impaired insulin clearance and degradation, impaired counterregulatory hormone responses, and nutritional deprivation." (PMID 40019498, 2025). "Several studies indicate that this combination not only helps improve glycemic control but also reduces the associated risks typically linked to insulin alone, such as weight gain and hypoglycemia." (PMID 40863575, 2025). "SGLT2 inhibitors promote glucosuria by inhibiting glucose reabsorption in the proximal renal tubule, and the associated suppression of insulin secretion and stimulation of glucagon secretion protect against hypoglycemia." (PMID 40731782, 2025). "The likelihood of falls is increased in those receiving insulin therapy, which itself is associated with an increased risk of hypoglycemia." (PMID 40309264, 2025). "Considering the extended dosing interval and prolonged duration of action associated with insulin efsitora, there is potential for concerns regarding prolonged hypoglycemia, delayed recovery from hypoglycemic episodes, and recurrent hypoglycemia." (PMID 41476918, 2025). "Initial laboratory workup should include serum insulin, C-peptide, proinsulin, and cortisol levels to determine the cause of hypoglycemia." (PMID 40376359, 2025). "Studies in patients with T1D have shown that insulin degludec reduces the risk of nocturnal hypoglycemia by 25% compared to insulin glargine, whereas the incidence of daytime hypoglycemia was comparable between the two groups." (PMID 40574081, 2025). "The improvement in insulin sensitivity by endurance training in T1D can increase the risk of hypoglycemia for many hours after the sessions, especially overnight." (PMID 39998445, 2025).
Hypoglycemia (continued). "This retrospective study was strengthened by the matched cohort design, which adjusted for important physiologic covariates, including the increased risk of hypoglycemia in new-onset T1D as children enter remission and require less exogenous insulin." (PMID 40990290, 2025). "While the risk of hypoglycemia has been improved through the use of insulin analogs, the frequency of insulin injections has remained at once daily since the approval of insulin glargine 24 years ago." (PMID 40156735, 2025). "More recently, medications that interfere with the insulin signaling pathway have been considered to address hypoglycemia caused by NICTH." (PMID 40648766, 2025). "These tumors cause hypoglycemia provoked by excessive insulin production, which manifests clinically as affected behavior, memory loss, palpitations, tremors, and diaphoresis, potentially resulting in seizures, loss of consciousness, coma, or death." (PMID 40405975, 2025). "The first limitations is the need to administer insulin as an injectable, continued risk of hypoglycemia, and the high frequency of its administration." (PMID 40156735, 2025). "Additional meta-analysis, which examined short and long-term outcomes of metformin compared with insulin, demonstrated a reduced risk for neonatal hypoglycemia and pregnancy-induced hypertension." (PMID 40235646, 2025). "In these cases, the tumor's insulin secretion is triggered predominantly by nutrient intake, leading to an exaggerated postprandial insulin response that causes hypoglycemia." (PMID 40124204, 2025). "The lower incidence of hypoglycemia after the SE bolus at 180 and 300 min postprandially suggests that the SE bolus provides more balanced insulin delivery, reducing the risk of late postprandial hypoglycemia." (PMID 41156539, 2025). "Physiologically, morning exercise occurs during a time of relatively low circulating insulin levels and heightened insulin sensitivity, particularly in adolescents, which can increase the risk of hypoglycemia." (PMID 41026404, 2025). "Among the various stimuli-responsive types, glucose-responsive delivery of insulin holds significant importance for blood glucose control since it can dynamically maintain normoglycemia and reduce the risk of hypoglycemia." (PMID 40292663, 2025). "Insulinoma is the most common functional pancreatic islet cell tumor, secreting insulin and causing hypoglycemia, with a wide range of clinical presentations." (PMID 40475052, 2025). "Insulin therapy has been implicated in an increased risk of severe hypoglycemia, which can adversely affect immune responses and contribute to poorer outcomes during infections." (PMID 40863575, 2025). "When faced with refractory hypoglycemia associated with low insulin and low C-peptide levels, it is important to look for other rare diagnoses and to involve an endocrinologist." (PMID 40535137, 2025). "During prolonged and intense physical activities, such as marathons, the body’s increased glucose utilization and enhanced insulin sensitivity can cause hypoglycemia." (PMID 40217942, 2025). "For example, at more negative cumulative differences, where the average glucose is also lower, GLUCOSE suggests less insulin to mitigate the risk of hypoglycemia." (PMID 40425725, 2025). "Other AEs are hypoglycemia, principally when the drug is associated with insulin; hypotension; AKI; and diabetic ketoacidosis (DKA)." (PMID 40649730, 2025). "In particular, individuals with T1D must carefully adjust their insulin doses around exercise, as the risk of hypoglycemia − sometimes occurring even hours after PA − remains a significant concern." (PMID 41026404, 2025). "GLP‐1RA therapies, in particular, improve glycemic control, promote weight loss, and have a low risk of hypoglycemia, except when used in combination with insulin or sulfonylureas." (PMID 40309616, 2025).
Hypoglycemia (continued). "Hepatic glycogen depletion, impaired gluconeogenesis due to hepatocyte dysfunction, and insulinemia caused by increased insulin secretion and decreased degradation make patients prone to hypoglycemia, which can promote the occurrence of hepatic encephalopathy." (PMID 41586212, 2025). "Improved glycemic control through physical activity increases insulin sensitivity but also heightens the risk of hypoglycemia, which can affect autonomic responses." (PMID 40806227, 2025). "Ultimately, insulin pump users should be aware of the theoretical increase in insulin delivery and risk of hypoglycaemia during ascent and adjust their glucose monitoring and carbohydrate ingestion appropriately." (PMID 39496965, 2025). "Elevated insulin (≥6 μU/mL) and C-peptide (≥0.2 nmol/L) levels in the presence of hypoglycemia are highly suggestive of insulinoma, following the exclusion of other causes such as exogenous insulin or hypoglycemic agents." (PMID 39968426, 2025). "Insulin therapy offers superior glycemic control compared to oral agents but carries a higher risk of hypoglycemia and weight gain." (PMID 40959330, 2025). "In SPKT recipients, an HbA1c in the low-to-mid 6% range reflects physiological insulin secretion, typically associated with minimal risk of severe hypoglycaemia and lower glycaemic variability." (PMID 41536836, 2025). "After excluding other causes of hypoglycaemia (liver disease, infection, insulinoma, new-onset diabetes mellitus type 1, insulin use, adrenal insufficiency...), we found cases in the literature about paraneoplastic syndromes that cause hypoglycaemia." (PMID 39931615, 2025). "Insulin use was strongly associated with post-coital hypoglycemia, with 28.3% of insulin users reporting such events compared to only 3.0% of non-insulin users (p<0.001)." (PMID 41030722, 2025). "AID features, like adjustable glucose targets and temporary insulin delivery modulation, can help to mitigate the risk of hypoglycemia when activated 1–2 h before physical activity." (PMID 40217942, 2025). "The usage of premixed insulin can reduce the time of injection in elderly diabetic patients while reducing the risk of hypoglycemia in patients with cognitive dysfunction to a certain extent." (PMID 40260392, 2025). "Although early, intensified blood glucose control can delay the progression of DN to a certain extent, impaired kidney function can lead to the accumulation of exogenous insulin and oral hypoglycemic drugs in the body, increasing the risk of hypoglycemia." (PMID 40114703, 2025). "Preservation of beta cell function would reduce the dependency of external insulin therapy and minimise the risk of hypoglycaemia, diabetic ketoacidosis and long-term complications." (PMID 41224288, 2025). "The first 15 people in this study (5 in each arm) were monitored for the potential risk of hypoglycemia by testing a fingerstick blood glucose level at two time points within 90 ​min of the first dose of intranasal insulin." (PMID 40253245, 2025). "Specifically, a significant association was identified between VPA and nocturnal hypoglycemia events when the daily insulin dose was at or above 1.04 units per kilogram of body weight per day (P = .016)." (PMID 38954647, 2025). "Quantifying carbohydrate intake enables patients and healthcare providers to adjust medication dosages appropriately, minimizing glycemic excursions and the risk of hypoglycemia, particularly with insulin secretagogues." (PMID 39859337, 2025). "We performed these tests to exclude other causes of hypoglycaemia, for example, insulinoma (C-peptide and insulin) and adrenal disease." (PMID 39931615, 2025). "Although intensive insulin therapy can effectively lower blood sugar, overly lax management will increase the risk of hypoglycemia, which is also consistent with the keyword clustering." (PMID 41496776, 2025).
Hypoglycemia (continued). "The result showed that the FA elicited both the mildest glycemic and insulinemic responses in terms of early postprandial glucose rise, hypoglycemia risk, insulin peak, and insulin sensitivity among all samples." (PMID 41300026, 2025). "The current discussion in T2DM therapeutics revolves around the difficulties in creating convenient oral insulin with minimal risk of hypoglycemia." (PMID 39815320, 2025). "An acquired functional decrease in GH production and GH response to stimuli (such as insulin-induced hypoglycemia, arginine, arginine-GHRH, sleep, or exercise) is linked to obesity; this decrease is reversible following substantial weight loss." (PMID 39981480, 2025). "Patients present with fasting hypoglycaemia caused by suppression of endogenous insulin, ketones, growth hormone, and insulin receptors." (PMID 41329563, 2025). "Factitious hypoglycemia, associated with insulin secretagogues, has been reported in multiple clinical scenarios, including medication errors and cross-reactivity in insulin testing." (PMID 39030378, 2025). "This design enables selective insulin release only above the desired glycemic thresholds, a key feature for minimizing hypoglycemia risk in glucose-responsive insulin delivery systems." (PMID 40807234, 2025). "As a result, the insulin peak persists long after the meal’s glucose is absorbed, potentially causing hypoglycemia." (PMID 41471078, 2025). "Insulinomas are characterized by the excessive secretion of insulin from the tumor, leading to hyperinsulinemia and subsequently causing hypoglycemia." (PMID 40550558, 2025). "For instance, adding a GLP-1 RA to basal insulin therapy can reduce the risk of hypoglycemia when compared with adding prandial insulin to the regimen." (PMID 40863575, 2025). "Premixed insulin can improve glycemic control but can increase the risk of hypoglycemia and body weight gain, which can lead to poor adherence." (PMID 41268167, 2025). "Insulin therapy should be tailored to patient-specific factors, including lifestyle, blood glucose patterns, and hypoglycemia risk." (PMID 40190894, 2025). "It is impressive that the glycemic and insulinemic patterns of FA can be characterized as a lowered glucose peak, reduced risk of postprandial hypoglycemia, improved glycemic variability, decreased insulin secretion, and elevated insulin sensitivity." (PMID 41300026, 2025). "People with DKD have a higher risk of hypoglycaemia due to reduced insulin metabolism and clearance." (PMID 40939923, 2025). "Dextrose was administered in parallel to mitigate the risk of hypoglycemia during ongoing insulin therapy and facilitate ketone clearance." (PMID 40376133, 2025). "Neuroglycopenia has been produced by insulin-induced hypoglycemia or by mutating two major glucose transporters, namely GLUT1 at the blood–brain barrier and GLUT3 at neurons." (PMID 40119223, 2025). "Compared to the control groups of adult patients, the S1 group was associated with increased duration of insulin infusion, risk of hypoglycemia, and prolonged hospital stay." (PMID 41458864, 2025). "Treatment with insulin is associated with an increased risk of hypoglycaemia, which triggers a cascade of physiological responses that exacerbate vascular risk." (PMID 40130476, 2025). "Although once‐weekly insulin is more convenient, treatment decisions should consider individual patient factors such as hypoglycemia risk and tolerance to injection reactions." (PMID 40186384, 2025). "For DKA, hypoglycemia and hypokalemia were the most common complications, with lower-dose insulin regimens associated with reduced risks." (PMID 41262789, 2025). "Uncertainty persists regarding nocturnal hypoglycemia's association with PA levels vs moderating variables like excessive insulin dosing." (PMID 38954647, 2025). "The use of insulin was significantly associated with hypoglycemia (OR = 1.590, CI: 1.100–2.290, p = 0.010)." (PMID 41393767, 2025).
Hypoglycemia (continued). "It should minimise the risk of hypoglycaemia, ideally by replicating the counter-regulatory effect of glucagon, and adapt to diurnal variations in insulin sensitivity influenced by factors such as physical activity, sleep, and hormonal changes." (PMID 40718205, 2025). "For instance, insulin regimens can be adjusted based on individual insulin sensitivity, reducing hypoglycaemia risk and minimising weight gain." (PMID 40553147, 2025). "Overall, the consensus is that hypoglycemia, especially severe events, is not substantially increased with weekly regimens, and efsitora's risk of hypoglycemia appears comparable to daily insulin." (PMID 41152194, 2025). "These newer long-acting insulin analogues have a more physiological basal profile and a lower risk of hypoglycaemia than the first-generation long-acting insulin glargine." (PMID 40480914, 2025). "Conversely, low blood glucose levels indicated neurological symptoms caused by hypoglycemia beyond the threshold, likely due to a lesion that excessively secretes insulin, as the human brain relies solely on glucose as its energy source." (PMID 40475052, 2025). "In people with T1D, carbohydrate malabsorption increases the risk of mismatch between prandial insulin and serum glucose, which can alter post-prandial glucose patterns including an increased risk of hypoglycemia." (PMID 40990290, 2025). "While the risk of hypoglycaemia with SGLT2 inhibitor monotherapy is low, the risk of hypoglycaemia in patients receiving insulin, particularly those with CKD, is less well defined." (PMID 40036884, 2025). "In summary, both insulin icodec and glargine U100 induce comparable symptomatic hypoglycemia risk after double or triple dose administration, but icodec induces slightly greater endocrine responses during hypoglycemia." (PMID 39810242, 2025). "The immediate cause of death of the deceased with insulin-dependent Type I diabetes was hypoglycemia caused by the effects of methamphetamine and insulin." (PMID 38965163, 2025). "Both our univariate and multivariate analyses supported these findings, reinforcing that elevated HbA1c levels and insulin therapy are critical risk factors for hypoglycemia in diabetic patients." (PMID 41040859, 2025). "Nevertheless, insulin therapy requires close monitoring to minimize hypoglycemia risk and manage the burden of injections." (PMID 40995094, 2025). "GLP‐1 receptor agonists not only contribute to HbA1C reduction to a greater extent, but promote weight loss and are associated with a low risk of hypoglycemia when compared with insulin." (PMID 40214296, 2025). "Risk factors for hypoglycaemia include: an excessive dose of insulin, a skipped meal, a reduced portion of carbohydrates, too intensive unplanned physical activity, alcohol consumption and aiming at the fast normalisation of glycaemia in blood." (PMID 41040854, 2025). "For continuous infusion, 10% glucose (500 mL) with 10 units of regular insulin is used, with the infusion rate adjusted based on the total infusion volume, hypoglycemia risk, and clinical context." (PMID 40705102, 2025). "One meta-analysis published in 2024 analyzed the effects of disease-modifying immunotherapy on C-peptide and HBA1c levels along with daily insulin dosage, and the risk of hypoglycemia." (PMID 40215252, 2025). "Third, the target fasting glucose ranges (80–130, 80–100, and 80–120 mg/dL) differed among the three studies, potentially leading to more frequent insulin dose escalations and increasing the risk of hypoglycemia." (PMID 40186384, 2025). "Compared with the fresh apple, the freeze-dried samples behaved better in terms of early postprandial glucose rise, hypoglycemia risk, insulin peak, and insulin sensitivity." (PMID 41300026, 2025).